SORBS3 (sorbin and SH3 domain containing 3)
Description:
Vinexin alpha isoform promotes up-regulation of actin stress fiber formation. Vinexin beta isoform plays a role in cell spreading and enhances the activation of JNK/SAPK in response to EGF stimulation by using its third SH3 domain.
Synonyms: SCAM-1; SCAM1; SH3D4; vinexin
Tractability: PROTAC: ubiquitination databases record sites on it; its protein half-life has been measured.
Gene: Protein-coding gene on chromosome 8 (22,544,986 to 22,575,788, forward strand). Ensembl gene ENSG00000120896.
Subcellular location: Cell junction (Isoform Alpha); Cytoplasm, cytoskeleton; Cell junction (Isoform Beta); Nucleus
Subcellular location (Human Protein Atlas): Cell Junctions; Plasma membrane
Pathways (Reactome):
Muscle contraction: Smooth Muscle Contraction
Gene Ontology:
Molecular function: protein binding; vinculin binding; protein-macromolecule adaptor activity; structural constituent of cytoskeleton
Biological process: positive regulation of stress fiber assembly; cell adhesion; cell-substrate adhesion; cytoskeleton organization; positive regulation of cytoskeleton organization
Cellular component: focal adhesion; cell-substrate junction; cytoplasm; cytosol; nucleus; plasma membrane; anchoring junction; cytoskeleton
Genetic constraint (gnomAD): Loss-of-function variants: 67 observed, 93.9 expected, observed/expected ratio (o/e) 0.71, 90% interval 0.58 to 0.87. The upper end of that interval is the gene's LOEUF score, 0.87, which puts it in group 3 of 6, group 1 being the genes least tolerant of losing a copy. Missense variants: 951 observed, 904.93 expected, observed/expected ratio (o/e) 1.05, 90% interval 1 to 1.11. Synonymous variants: 394 observed, 352.22 expected, observed/expected ratio (o/e) 1.12, 90% interval 1.03 to 1.22.
Homologues: Orthologues: chimpanzee SORBS3 (99% identical), macaque SORBS3 (89% identical), rabbit SORBS3 (83% identical), guinea pig SORBS3 (82% identical), mouse Sorbs3 (81% identical), rat Sorbs3 (80% identical), dog SORBS3 (76% identical), pig SORBS3 (69% identical), zebrafish sorbs3 (34% identical), tropical clawed frog sorbs3 (29% identical), Caenorhabditis elegans sorb-1 (21% identical), Caenorhabditis elegans B0303.7 (11% identical), and 3 more. Paralogues in human: SORBS1 (35% identical), SORBS2 (30% identical), SH3D19 (16% identical), SH3RF1 (16% identical), SH3RF3 (16% identical), SH3RF2 (12% identical), NCF4 (9% identical), SH3GL1 (9% identical), SH3GL2 (9% identical), SH3GLB2 (8% identical), SH3GL3 (8% identical), SH3GLB1 (7% identical).
Diseases named in the same sentence as SORBS3 in open-access papers:
SORBS3 is named in the same sentence as 14 diseases in open-access papers, as found by Europe PMC text mining. Sharing a sentence is not in itself a finding about the gene and the disease. The quoted sentences say what the papers report.
Alzheimer disease (3 papers, 2007 to 2022). A progressive, neurodegenerative disease characterized by loss of function and death of nerve cells in several areas of the brain leading to loss of cognitive function such as memory and language. "Genomic mutations in Sorbin and SH3 Domain Containing 3 (SORBS3) that may regulate cell proliferation were associated with Alzheimer’s disease." (PMID 34182925, 2021). "The thromboxane A2 receptor and Sorbin SH3 domain containing 3 (Sorbs3) genes were found to be highly methylated in Alzheimer’s disease." (PMID 35053088, 2022). "Therefore, the significant DNA methylation changes in Alzheimer's disease, including the decrease of S100A2 and increase in SORBS3 CpG methylation, appear to represent accelerations of the normal, age-associated DNA methylation changes in these genes." (PMID 17878930, 2007).
hepatocellular carcinoma (3 papers, 2019 to 2023). A malignant tumor that arises from hepatocytes. "However, SORBS3 recently emerged as a tumor suppressor gene cooperating to inhibit interleukin-6 signaling in hepatocellular carcinoma and is associated with HCC progression." (PMID 31443224, 2019). "Among the hubs, SORBS3 could co-activate ERα signaling to repress STAT3 signaling in hepatocellular carcinoma; however, the potential activation of ERα in luminal B BC requires further analysis." (PMID 37483500, 2023). "Specifically, SORBS3 has been identified as a tumour suppressor in hepatocellular carcinoma, while our findings indicate increased SORBS3 expression could promote an age-related decline in cellular (and especially neuronal) fitness." (PMID 34848853, 2022).
Obesity (3 papers, 2016 to 2022). Accumulation of substantial excess body fat. "We have previously detected differences associated with SORBS3 in individuals with obesity and insulin resistance, and the present study provided further evidence of alterations in SORBS3 in response to weight loss by surgical intervention." (PMID 28883895, 2017). "We set out to further establish the relationship between SORBS3 methylation and gene expression changes with obesity through a surgical weight-loss intervention." (PMID 28883895, 2017). "Our previous study had identified SORBS3 as an obesity-associated gene, whose expression may be epigenetically regulated." (PMID 28883895, 2017). "However, it is unclear whether the reduction in SORBS3 observed in obesity could be rescued through surgical weight-loss interventions such as RYGB." (PMID 28883895, 2017). "Changes in SORBS3 expression after surgery were correlated with obesity measures and fasting insulin levels." (PMID 36397166, 2022). "Previously, we had shown increased methylation (5.0 to 24.4%) and decreased gene expression (fold change − 1.9) of SORBS3 with obesity (BMI > 30 kg/m2) compared to lean controls." (PMID 28883895, 2017). "Specifically, we had shown an increase in skeletal muscle promoter methylation and a decrease in mRNA expression of SORBS3 with obesity." (PMID 28883895, 2017). "Changes in SORBS3 gene expression post-surgery were correlated with obesity measures and fasting insulin levels (r = 0.5 to 0.8; P < 0.05)." (PMID 28883895, 2017). "Increased DNA methylation in the promoter and 5′UTR of SORBS3 with obesity were originally identified in our previous study." (PMID 28883895, 2017). "The qRT-PCR confirmed the microarray results demonstrating a decrease in gene expression of SORBS3 in the participants with obesity (fold change −1.4; P = 0.01)." (PMID 27437034, 2016). "Merging across our omic datasets identified sorbin and SH3 domain containing 3 (SORBS3) as a novel obesity gene." (PMID 27437034, 2016). "We believe that changes in SORBS3 expression may be connected to our proposed model since it is a cytoskeletal gene that was reduced with obesity." (PMID 28883895, 2017). "The reduction in SORBS3 gene expression seen in our group with obesity may lead to a delayed response in growth-factor signaling." (PMID 27437034, 2016). "The changes in obesity with SORBS3 expression coding for vinexin may be connected to our proposed model by regulating the plasticity of cytoskeletal elements." (PMID 27437034, 2016). "Although our study found reduced expression of SORBS3 in the vastus lateralis of individuals with obesity, it is tempting to speculate that there may be a similar remodeling and fibrotic affect due to vinexin β." (PMID 27437034, 2016). "Therefore, we hypothesize that a change in expression of SORBS3 in obesity could be contributing to altered skeletal muscle structure." (PMID 27437034, 2016). "SORBS3 is decreased in expression in obesity, and this in part may be due to increased methylation." (PMID 27437034, 2016). "Our previously published study identified a novel gene, sorbin and SH3 domain containing 3 (SORBS3), that was differentially methylated with obesity." (PMID 28883895, 2017).
cervical cancer (1 paper, 2022). A primary or metastatic malignant neoplasm involving the cervix. "During ongoing screening for autophagy modulators, we investigated vinexin using siRNA against SORBS3 (siSORBS3) in HeLa (human cervical cancer), SH-SY5Y (human neuroblastoma) and RPE (human retinal pigment epithelium) cells." (PMID 34848853, 2022).
diabetes (1 paper, 2025). "Increased expression of Sorbs3 (p = 5.5 × 10–18), Ptpre (p = 0.006) and decreased expression of Pdk4 (p = 0.048) and Dnmt3b (p = 1.2 × 10–11) in VSG GK rats further support the involvement of epigenetic mechanisms in diabetes remission and in the long-term adaptation to bariatric surgery." (PMID 41360887, 2025).
liver fibrosis (1 paper, 2025). "Inhibiting SORBS3‐K479la can alleviate liver fibrosis caused by overtraining." (PMID 40984037, 2025).
tumor (7 papers, 2014 to 2024). "A novel transcript of SORBS3 is more complex in terms of alternative splicing; SORBS3 is also associated with poor outcomes of patients and its product has tumor suppressive activities." (PMID 34480063, 2021). "Mechanistically, ZNF704 function as an oncogene by down-regulates SORBS3, which we demonstrated is a tumor suppressor in UM, and in turn activates PI3K/AKT/mTOR signaling pathway." (PMID 37038184, 2023). "Finally, recent investigations have shown RBP sorbin and SH3 domain-containing (SORBS) proteins, including SORBS1, SORBS2 and SORBS3, exhibit tumor suppressive function in cancer growth." (PMID 37038184, 2023). "We subsequently validated the expression of SORBS3 in tumor and adjacent choroid tissues." (PMID 37038184, 2023). "Loss of 8p involving the DLC1, CCDC25, ELP3, PROSC, SORBS3, SH2D4A genes associated with poor outcomes for HCC; in vitro and in vivo analysis indicated that the PROCS, SH2D4A and SORBS3 genes have tumor-suppressive activities and the DLC1 gene is a known tumor suppressor gene." (PMID 34103027, 2021). "Moreover, expression of SORBS3 is downregulated by ZNF704 and knockdown of SORBS3 restored tumor cell viability in ZNF704 silenced cells." (PMID 37038184, 2023).
SORBS3 also shares sentences with these, for which no sentence is quoted: atherosclerosis (1 paper); cancer (1); glioblastoma (1); infection (1); Insulin resistance (1); neuroblastoma (1); schizophrenia (1).